VXN (vexin)
Description:
Required for neurogenesis in the neural plate and retina. Strongly cooperates with neural bHLH factors to promote neurogenesis.
Synonyms: C8orf46; MGC33510
Tractability: Antibody: UniProt places it where antibodies can reach, with medium confidence; its Gene Ontology location is reachable by antibodies, with medium confidence.
Gene: Protein-coding gene on chromosome 8 (66,492,326 to 66,518,524, forward strand). Ensembl gene ENSG00000169085.
Subcellular location: Cell membrane; Nucleus
Subcellular location (Human Protein Atlas): Nuclear speckles
Gene Ontology:
Molecular function: protein binding
Biological process: neurogenesis; neuron differentiation
Cellular component: nucleus; plasma membrane
Genetic constraint (gnomAD): Loss-of-function variants: 6 observed, 19.74 expected, observed/expected ratio (o/e) 0.3, 90% interval 0.17 to 0.6. The upper end of that interval is the gene's LOEUF score, 0.6, which puts it in group 2 of 6, group 1 being the genes least tolerant of losing a copy. Missense variants: 238 observed, 256.66 expected, observed/expected ratio (o/e) 0.93, 90% interval 0.83 to 1.03. Synonymous variants: 120 observed, 99.37 expected, observed/expected ratio (o/e) 1.21, 90% interval 1.04 to 1.4.
Homologues: Orthologues: chimpanzee VXN (100% identical), macaque VXN (97% identical), rabbit VXN (86% identical), guinea pig VXN (84% identical), mouse Vxn (83% identical), pig VXN (81% identical), rat Vxn (75% identical).
Diseases named in the same sentence as VXN in open-access papers:
VXN is named in the same sentence as 2 diseases in open-access papers, as found by Europe PMC text mining. Sharing a sentence is not in itself a finding about the gene and the disease.
VXN shares sentences with these, for which no sentence is quoted: amyotrophic lateral sclerosis (1 paper); tumours (1).